LEP (leptin)
Diseases named in the same sentence as LEP in open-access papers (continued):
Sharing a sentence is not in itself a finding about the gene and the disease.
type 2 diabetes (continued). "Based on our data, the most likely explanation for discordant patterns in type 1 vs type 2 diabetes are the metabolic and endocrine parameters specifically associated with AI—but not RBCD, including BMI, HOMA-IR, C-peptide and leptin values." (PMID 41408588, 2025). "In this study, exposure to type 2 diabetes, but not gestational diabetes, impacted cord blood levels of glucose, insulin and leptin and birthweight." (PMID 40045330, 2025). "Visceral white adipose tissue (abdomen and upper body) appears to be the major source of inflammatory markers in type 2 diabetes (cytokines, TNF-alpha, IL-1, IL-6, IL-10, leptin, adiponectin, monocyte chemoattractant protein, angiotensinogen, resistin, chemokines, etc.)." (PMID 37298118, 2023). "This is in line with the results of an earlier study among non-obese and obese subjects with type 2 diabetes in Tanzania and Sweden, which showed that leptin concentrations were 50% higher in the Tanzanians." (PMID 37555575, 2023). "In a cohort of subjects with type 2 diabetes, the circulating CCN4 levels correlated positively with fat mass, serum leptin, resistin, and visfatin levels, suggesting that CCN4 may contribute to the metabolically-induced tissue inflammation." (PMID 33946738, 2021). "Obese subjects with type 2 diabetes had lower leptin but higher hsCRP levels compared with obese non-diabetic controls." (PMID 29422086, 2018). "In this study, obese subjects with type 2 diabetes had lower serum leptin but higher hsCRP concentrations than obese non-diabetic individuals." (PMID 29422086, 2018). "The purpose of this study was to evaluate serum leptin and hsCRP concentrations in Ghanaian obese subjects with and/or without type 2 diabetes and to find out the extent to which their levels are influenced by the underlying disorder." (PMID 29422086, 2018). "This study aimed to evaluate serum leptin and high sensitivity C-reactive protein (hsCRP) concentrations in obese Ghanaians with or without type 2 diabetes and to find out the extent to which their levels are influenced by underlying disorders." (PMID 29422086, 2018). "The present study evaluated the impact of serum leptin and hsCRP levels in obese Ghanaian subjects with and/or without type 2 diabetes." (PMID 29422086, 2018). "Obese persons have high blood leptin levels, but they also show leptin resistance and hence, because insulin secretion is not well regulated either, with time can develop type II diabetes." (PMID 28651594, 2017). "In patients with type 2 diabetes, leptin levels were not altered after 6 weeks of resistance exercise." (PMID 28288611, 2017). "After induction of type 2 diabetes by NA-STZ, serum ALP, SGPT and SGOT levels increased and serum leptin level decreased compared to control group and these variations were significant for SGPT (p<0.05), ALP and leptin (p<0.01)." (PMID 28348972, 2017). "It has been shown that treatment with recombinant human leptin does not improve insulin sensitivity in obese patients with type 2 diabetes, contrary to what happens in patients with severe leptin deficiency." (PMID 27216013, 2016). "In line with earlier reports we observed that in human patients the circulating levels of leptin are positively correlated to BMI, type 2 diabetes and consequences thereof such as elevated HbA1c, but not CAD, age or plasma cholesterol and triglycerides." (PMID 27139713, 2016). "In males the relationship between leptin and IHD was independent of traditional risk factors which was in line with earlier trials in men with high risk but not necessarily restricted to type 2 diabetes." (PMID 25994184, 2015). "Protein tyrosine phosphatase (PTP) 1B, a negative regulator of the insulin and leptin signaling pathways, is currently considered a promising target for the development of novel therapeutic approaches used to treat insulin-resistant type 2 diabetes mellitus (IR-T2DM)." (PMID 24555682, 2014).
type 2 diabetes (continued). "The main finding of this study was that non-obese subjects with type 2 diabetes had lower serum leptin concentrations compared to non-diabetic controls, as was previously observed in moderately obese diabetic subjects." (PMID 23853613, 2013). "This study was undertaken to investigate whether the plasma levels of leptin, ghrelin and inflammatory cytokines are associated with BMI (reflecting nutritional status) in TB patients with and without type 2 diabetes (T2DM)." (PMID 24260344, 2013). "The interruption of the liver leptin-AMPK-ACC signaling pathway might be one of the glucose and lipid metabolism disorders found in type 2 diabetes." (PMID 24455748, 2013). "This remarkable result indicates that NO may help to compensate the energy metabolism by improving leptin and insulin levels, and HOMA-IR, HOMA-β in type 2 diabetes." (PMID 23251156, 2012). "In subjects with and without type 2 diabetes, PPARD +294T>C was associated with BMI, HDL-C, leptin, and TNF-alpha and was dependent on gender." (PMID 23039238, 2012). "It is important to mention that in this type 2 diabetes obese animal model, leptin is absent and there is an increase in circulating TNFα." (PMID 22662132, 2012). "The levels of MIF, insulin, ghrelin, leptin, glucagon, resistin and adipsin are similar in type 2 diabetes and CHD patients whereas IL-1α, IL-2R, IL-12, IL-18, HGF, and PAI-1 are higher in CHD patients than in type 2 diabetes patients (with p-value <0.01)." (PMID 22745767, 2012). "Leptin has been shown to be an independent predictor of type 2 diabetes in some but not in all studies." (PMID 23251619, 2012). "Exposure of human islets to glucose, leptin, or free fatty acids (FFA) increases the production and release of IL-1β, hence, therapy targeting IL-1β is a logical choice in protecting the beta-cell in type 2 diabetes." (PMID 22922276, 2012). "In summary, we have shown that central leptin is an effective anti-diabetic therapy in a non-obese model of type 2 diabetes." (PMID 21379576, 2011). "Type II diabetes is also not a statistically significant factor affecting leptin levels." (PMID 36981858, 2023). "Thus, the lack of LEPTIN negatively affects insulin mediated glucose metabolism, further obstructing glucose regulation and contributing to type II diabetes." (PMID 37705071, 2023). "However, a recent systematic review of probiotic intervention in patients with prediabetes and type 2 diabetes mellitus reported no significant alterations in adiponectin and leptin levels." (PMID 36499312, 2022). "Perhaps recombinant leptin in non-obese individuals with type II diabetes would have a different outcomes, but future research is needed to confirm or deny these speculations." (PMID 35628271, 2022). "Serum leptin level is also shown to be lower in non-obese subjects with type 2 diabetes." (PMID 36295022, 2022). "However, not all genetic correlations, including those with leptin levels and type 2 diabetes, remained significant after adjusting for BMI." (PMID 34594363, 2021). "Ob/ob mice that do not express leptin, leptin receptor-deficient db/db mice, and Zucker diabetic fatty rats with a nonfunctional db receptor and a mutation affecting transcription in pancreatic β cells are frequently employed rodent models of type 2 diabetes mellitus (T2DM)." (PMID 32829466, 2020). "Our mice at most time points were likely pre‐diabetic given their leptin levels, but are unlikely to have developed type 2 diabetes, which could explain the less severe phenotype we observed as compared to the Zucker Diabetic Fatty rats." (PMID 31660698, 2019). "We hypothesized that obese subjects with type 2 diabetes will have higher leptin and hsCRP levels compared with their obese non-diabetic counterparts." (PMID 29422086, 2018). "High plasma leptin predicted low insulin sensitivity in a young group of women with recent GDM, suggesting that leptin signaling may be more important than low-grade inflammation as a contributor to type 2 diabetes." (PMID 29951553, 2018).
type 2 diabetes (continued). "The drugs for type 2 diabetes metformin and berberine enhanced LSR expression in endometrial cancer cells and normal HEEs and prevented the cell migration and invasion induced by downregulation of LSR in those treated with the siRNA or leptin in endometrial cancer cells." (PMID 27036040, 2016). "Similarly, leptin treatment did not have a clinically important effect on insulin action in obese people with newly diagnosed type 2 diabetes." (PMID 24987413, 2014). "Although there was no certain reason for increase or decrease of serum leptin levels in type 2 diabetes compared to non-diabetics, a possible explanation for reducing leptin levels in diabetic subjects is a difference in the fat distribution between 2 groups which was not determined in this study." (PMID 23853613, 2013). "The present study evaluates serum leptin levels in non-obese subjects with type 2 diabetes." (PMID 23853613, 2013). "We also showed that serum leptin was significantly correlated with cardiometabolic health indices (especially in the NW mothers), which according to the literature, are predictors of the risk of developing CVD, type 2 diabetes or MetS among non-lactating individuals." (PMID 38668349, 2024). "Due to single-gene mutations that lead to the lack of action by the satiety factor leptin or its cognate receptor, these rodents spontaneously develop severe hyperphagia leading to obesity and manifest some type 2 diabetes mellitus (T2DM)-like characteristics." (PMID 36678910, 2023). "Studies have indicated that myosteatosis is associated with insulin resistance, type 2 diabetes mellitus (T2DM), dyslipidemia and cardiometabolic diseases, and there was also a link between skeletal muscle density and biomarkers of inflammation, such as CRP, IL-6, TNF-α, adiponectin and leptin." (PMID 35837298, 2022). "Leptin levels in pericardial fluid and plasma were correlated to most of the same patient characteristics while APN in pericardial fluid was unlike in the plasma not correlated to age, body mass index, type 2 diabetes, plasma triglycerides and CAD." (PMID 27139713, 2016). "So possibly in patients with type 2 diabetes, leptin and TNF-α status can not be explained by the ‘‘cytokine–leptin hypothesis’’." (PMID 24260344, 2013).
Hypertension (492 papers, 2005 to 2026). The presence of chronic increased pressure in the systemic arterial system. "Although our cohort comprised exclusively patients with hypertension, the observed inverse association between leptin and endothelial function is biologically plausible beyond the hypertensive setting." (PMID 41470134, 2025). "In summary, this study demonstrated that elevated serum leptin levels are independently associated with vascular reactivity impairment in patients with hypertension, as assessed by digital thermal monitoring." (PMID 41470134, 2025). "Older preclinical studies have shown that adipocyte-derived leptin contributes to obesity-associated hypertension in males via inducing endothelial dysfunction and increasing sympathetic activity." (PMID 39858537, 2025). "DKD models fall into several categories: STZ-induced models of T1DM-DKD; leptin/leptin-receptor deficiency-induced hyperphagia, obesity, and renal disease; nephrectomy-based models; and models that combine diabetes, obesity, and hypertension." (PMID 41157299, 2025). "The correlation of leptin with blood pressure values and adipose tissue mass brought into discussion a new possible therapeutic intervention for treating hypertension associated with obesity." (PMID 39062887, 2024). "Serum leptin levels in our study population were significantly associated with gender, BMI and hypertension, in accordance with previous evidence on other populations." (PMID 38686200, 2024). "In conclusion, these data suggest that leptin plays a pathogenic role in the development of hypertension in SLE, in part, by promoting the expansion of inflammatory DN T cells and the infiltration of T cells into the kidneys." (PMID 38031726, 2023). "Obesity-related hypertension (ORH) and early onset essential hypertension (EH) have been shown to be associated with serum leptin levels." (PMID 37240998, 2023). "Circulating levels of leptin were significantly higher in subjects with a high risk of CV and who were affected by MetSyn and hypertension." (PMID 35887363, 2022). "Clinical trials have shown that elevated serum leptin levels are associated with the risk of hypertension." (PMID 35488267, 2022). "A clinical trial showed that an increased concentration of leptin increases the risk of myocardial ischemia and cardiomyocyte apoptosis and is accompanied by a more frequent occurrence of arterial hypertension." (PMID 35327129, 2022). "From a practical and clinical point of view, maternal serum adiponectin and leptin can be used as markers to identify women with a predisposition to developing hypertension during pregnancy and thus can permit early detection." (PMID 36034841, 2022). "Numerous studies have shown leptin to induce glomerulosclerosis and hypertension, both risk factors to CKD." (PMID 36726470, 2022). "Leptin can stimulate the sympathetic nervous system, and elevated leptin levels can lead to high blood pressure, which is a risk factor for cardiovascular diseases." (PMID 36698957, 2022). "Patients with CGL deficient in adipose tissue and leptin present with severe cardiovascular alterations including hypertension, coronary artery disease, hypertrophic cardiomyopathy and autonomic impairment." (PMID 34638939, 2021). "Studies discussed in this review also showed associations between serum leptin concentration, hypertension, endothelial damage, atherosclerosis, inflammation, strokes, and CAD." (PMID 34178553, 2021). "The excess of circulating metabolically active compounds such as glucose, insulin, FFA, and leptin in obese women is likely to increase the risk of hypertensive disorders of pregnancy." (PMID 33869631, 2021). "In obese children, the elevation of CIMT has been associated with low levels of adiponectin, higher levels of leptin, increased C-reactive proteins with high sensitivity (hsCRP), higher levels of lipid, and hypertension." (PMID 33182462, 2020).
Hypertension (continued). "Another recent study shows association between leptin polymorphism and coronary artery disease and hypertension." (PMID 32272684, 2020). "In the Copenhagen City Heart Study, leptin was significantly associated with new‐onset hypertension with an odds ratio of 1.28." (PMID 31914480, 2020). "Future study will be needed to explore the associations between sex hormones, leptin, and the increased risk of hypertension in Chinese population." (PMID 32680562, 2020). "Higher odds of high blood pressure were associated with leptin (1.57 (1.08, 2.27)), and higher odds of abdominal obesity were associated with CRP (2.14 (1.33, 3.45)) only in men." (PMID 33374992, 2020). "We also found that the LG-H IUGR offspring exhibit increased risk for CVD at 4 months of age, manifesting as hypertension, increased abdominal fat, elevated leptin and total cholesterol concentrations." (PMID 30718791, 2019). "Leptin is a pleiotropic hormone which controls numerous organ systems and has been positively associated with hypertrophic cardiomyopathy, hypertension, and vascular inflammation in the context of obesity." (PMID 31656583, 2019). "Recently a similar observation was made in a population of children and adolescents in which the risk of developing hypertension during a follow-up of six years was approximately doubled in subjects with a high leptin/adiponectin ratio." (PMID 31262082, 2019). "Logistic regression analysis was performed to test the associations of BDNF, musclin, leptin and irisin with hypertension." (PMID 31133682, 2019). "A more detailed synopsis of this potential pathway for leptin-induced aldosterone-mediated hypertension risk in premenopausal women has been reviewed by the authors previously." (PMID 31262349, 2019). "As demonstrated in experimental studies in human cells models, leptin also induces endothelial oxidative stress and reactive oxygen species formation, mechanisms known to increase the risk to develop hypertension." (PMID 31330870, 2019). "Abnormalities in the renin-angiotensin system and increased levels of various regulatory hormones, like insulin and leptin, have been consistently described to take place among the obese, although the causal link to hypertension is tenuous." (PMID 29320983, 2018). "Leptin has also been associated with thermogenesis and hypertension and is markedly elevated in the obese." (PMID 29320983, 2018). "Chronic central hyperleptinemia can cause maladaptations, like hypertension due to leptin's action on leptin receptors (LEPRs) in the dorsomedial hypothalamic nucleus." (PMID 29748097, 2018). "The aim of the present study is to investigate the associations between the SNP and two hypertension-related traits, lipids and leptin." (PMID 29338791, 2018). "Elevated plasma leptin levels or hyperleptinemia is associated with various health conditions including hypertension, pulmonary inflammation, and low-grade systemic inflammation and metabolic dysfunction in obese humans." (PMID 29675134, 2018). "Elevated leptin levels have been implicated in the development of hypertension in human and animal models." (PMID 29190710, 2017). "Another confusing insight in the suggestion that leptin contributes to the reversal of LVH is that hypertension is known to lead to LVH, but hypertension is associated with increased levels of leptin." (PMID 26064110, 2015). "Leptin is an indicator of total fat mass; thus, abnormal leptin levels are implicated in the pathophysiology of hypertension, atherosclerosis and coronary heart disease." (PMID 25754247, 2015). "The exact mechanism(s) by which leptin is associated with hypertension and the progression of cardiovascular diseases remains to be investigated as discussed in this work." (PMID 26557089, 2015). "Leptin is secreted in high concentrations as a result of the mechanical stretch associated with hypertension, and leptin alone is able to increase ROS generation." (PMID 26064110, 2015).